CA9 (carbonic anhydrase 9)
Diseases named in the same sentence as CA9 in open-access papers (continued):
Sharing a sentence is not in itself a finding about the gene and the disease.
cervical carcinoma (continued). "CA9 is a widely-used intrinsic hypoxia marker, and we and others have demonstrated its correlation with hypoxia in cervix cancer cell lines, although it has recently been reported that CA9 expression does not correlate with pimonidazole staining in two cervix cancer xenograft models." (PMID 27901496, 2017). "Survival significance of CA9 expression has been studied in cervical cancer but this remains unclear." (PMID 23927384, 2013). "Here we tested the hypothesis that CICs reside in CA9 positive fractions of solid cervical cancers by establishing limiting dilution assays (LDAs) of differentially-sorted CA9 populations from the OCICx models and determining their subsequent CIC frequency (CIF)." (PMID 27901496, 2017). "Therefore, the overexpression of CA9 in SiHa cervical cancer cells was analyzed." (PMID 29100431, 2017). "They tested these compounds for their ability to inhibit the enzyme carbonic anhydrase IX (CA9/CAIX) and their effects on human HCT-116 colon cancer and HeP2 cervical cancer cells." (PMID 40430417, 2025). "Among the five genes, the expression of ALOX12B and F5 was decreased, while that of CA9, FAR2 and TDO2 was relatively elevated in cervical cancer samples, as indicated by the IHC results." (PMID 35626004, 2022). "In current study, we identified a reliable metabolism-related signature composed of ALOX12B, CA9, FAR2, F5 and TDO2 for the prognosis and anti-tumor immunity in cervical cancer." (PMID 35626004, 2022). "CA9 is involved in HIF-1-target-gene expression, which can provide the theoretical basis for the use of oxygen as a cervical cancer treatment, but further experiments are required to examine this possibility." (PMID 36313765, 2022). "In the current study, the novel designed model with four genes (RNF130, CA9, DERL3, and VEGFA) yielded high specificity and sensitivity in identifying prognosis in the cervical cancer." (PMID 35935576, 2022). "We discovered that the CA9 SNP rs1048638 influences the expression of CA9 through the interaction between the 3′-untranslated region (UTR) of exon 11, where the SNP is located, and miR-34a, and influences the migration of cervical cancer cells." (PMID 29100431, 2017). "HIF-1α, c-Met, CA9 and GLUT1 expression were higher in cervical cancer than in CIN and normal cervix (all P < 0.001)." (PMID 23927384, 2013). "Of 179 cervical cancer specimens, 148 (82.6%) was available to confirm co-expression between HIF-1α and c-Met, 131 (73.1%) was available between HIF-1α and CA9, and 137 (76.5%) was available between HIF-1α and GLUT1." (PMID 23927384, 2013). "In the current study, the expression of HIF-1α and functionally related proteins, including c-Met, CA9 and GLUT1, were analyzed in cervical cancer patients by combined IHC and automated digital image analysis." (PMID 23927384, 2013). "Among them, CA9 is the most widely known hypoxia-inducible factor (HIIF) -1α target gene during hypoxia, which also provides a theoretical basis for oxygen treatment of cervical cancer." (PMID 36313765, 2022). "The findings obtained from qRT-PCR illustrated that the expression levels of VEGFA, CA9, and DERL3 in cervical cancer specimens were dramatically elevated in contrast with those in normal specimens, whereas the expression levels of RNF130 were lower contrasted to those in normal specimens." (PMID 35935576, 2022). "More importantly, we collected proteins from HPA and found that CA9 was highly expressed in cervical cancer tissues, but not expressed in normal cervical tissues." (PMID 36313765, 2022). "A pair of ceRNAs (CA9/ULBP2) could be involved in the carcinogenesis and development of cervical cancer, and the potential target might be hsa-miR-34a." (PMID 36313765, 2022).
cervical carcinoma (continued). "In addition, CA9 SNP rs1048638 increases the risk of cervical cancer, which might be due to an allele at CA9 rs1048638, which impairs miR-34a binding to the CA9 3′-UTR and desensitizes CA9 mRNA to miR-34a-dependent RNA degradation, in turn increasing CA9 expression." (PMID 36313765, 2022). "Furthermore, the molecular functional role of the binding between CA9 3′-UTR mRNA and miR-34a binding in cervical cancer requires further investigation." (PMID 29100431, 2017). "Notably, CA9 mRNA was significantly overexpressed in cervical carcinoma, tissues but not in normal cervix tissues." (PMID 36313765, 2022). "In addition, separate analysis of CA9 found that the ceRNA networks (CA9/ULBP2) might regulate the occurrence and development of cervical cancer, but additional experimental results are needed." (PMID 36313765, 2022). "In addition, due to the possible link between CAIX and HPV infection, it might be particularly meaningful to identify CA9 expression in cervical cancer cells." (PMID 33803236, 2021).
clear cell renal cell carcinoma (73 papers, 2003 to 2026). "It is worth mentioning that CA9 has been well described as a diagnostic marker for clear cell renal carcinoma (ccRCC), especially by showing high expression in metastastic ccRCC (mccRCC)." (PMID 23394073, 2013). "Moreover, CA9 has been well-described as a diagnostic marker for clear cell renal carcinoma (ccRCC), and it is highly expressed in metastatic ccRCC (mccRCC)." (PMID 23671581, 2013). "CA9 SNP patients with metastatic clear cell renal cell carcinoma may be associated with better survival and a greater opportunity to response to interleukin-2." (PMID 24349364, 2013). "CA9 is expressed on the surface of tumor cells in renal clear cell carcinoma, the most common form of renal cancer." (PMID 40723287, 2025). "Our previous analysis identified key diagnostic biomarkers for clear cell renal cell carcinoma (ccRCC), and found the top 2 essential genes in LASSO regression algorithm are CA9 and AXL." (PMID 41029360, 2025). "Loss-of-function mutations in the Von Hippel-Lindau gene are frequently found in clear cell renal cell carcinoma (ccRCC) leading to CA9 overexpression." (PMID 39768175, 2024). "Ca9 is described as a hypoxia-related protein that is overexpressed by clear cell renal cell carcinoma cells." (PMID 36975533, 2023). "When dealing with neoplasms characterized by cells with clear cytoplasm, CA9 is a helpful marker to exclude clear cell renal cell carcinoma." (PMID 35980471, 2022). "To target CA9, we developed dual antigen T cell engagers (DATEs) that were exquisitely specific for CA9-positive patient-derived clear cell Renal Cell Carcinoma (ccRCC) and GBM cells." (PMID 35874663, 2022). "CA9 has been found to play a critical part in the metastasis, recurrence and resistance of many cancers, including, clear cell renal cell carcinoma, hepatocellular carcinoma and prostate cancer." (PMID 32299152, 2020). "In the study for G250 monoclonal antibody, it has been displayed excellent specificity for CA9 in clear cell renal cell carcinoma (CCRCC) analysis." (PMID 26447758, 2015). "Published ELISA studies detected CA9 in serum of patients with renal clear cell carcinoma." (PMID 40723287, 2025). "In renal clear cell carcinoma, CA9 could be an independent prognostic tumour marker and a diagnostic biomarker." (PMID 32299152, 2020). "Furthermore, CA9 is also highly expressed in a large proportion of clear cell Renal Cell Carcinoma (ccRCC) in a hypoxia-independent manner where it is driven by stabilization and constitutive activation of HIF-1alpha signaling as a result of mutation of the von Hippel-Lindau (VHL) tumor suppressor." (PMID 35874663, 2022). "In clear cell renal cell carcinoma (ccRCC), the hypoxia-inducible PMP carbonic anhydrase IX (CA9) has been targeted with [177Lu-DOTA-hG250], enhancing immunotherapy efficacy and tumour selectivity." (PMID 40843709, 2025). "Consistent with this, KAT8 overexpression increased H4K16ac levels, reduced carbonic anhydrase 9 (CA9) expression, and promoted apoptosis in clear cell renal cell carcinoma." (PMID 40508066, 2025). "Metastatic clear cell renal cell carcinomas show nests of tumor cells surrounded by prominent delicate vessels and are positive for cytokeratin, EMA, PAX-8, and CA9." (PMID 32316685, 2020). "Carbonic anhydrase IX (CA9), a pH-regulating transmembrane protein, is highly expressed in solid tumors, and particularly in clear cell renal cell carcinoma (ccRCC)." (PMID 32824856, 2020). "Metastatic clear cell renal cell carcinomas show nests of tumor cells surrounded by prominent delicate sinusoidal vessels and are positive for cytokeratin, EMA, PAX-8, and CA9." (PMID 32316685, 2020). "CA9 is expressed in all clear-cell renal cell carcinoma but usually is not detected in most normal tissues." (PMID 41516250, 2025).
lung carcinoma (60 papers, 2002 to 2026). "Moreover, the CA9 SNP rs2071676 AG + GG was correlated to a lower tumor stage and lower risk for developing lymph node metastasis in lung carcinoma accompanied by wide type of EGFR." (PMID 32365566, 2020). "As the polymorphism of CA9 indicates a relatively fair outcome of lung carcinoma, the lower ratio of CA9 SNP in lung adenocarcinoma with L858R expression may be considered as a co-predictor for the progression and prognosis but the detail needs further investigation." (PMID 32365566, 2020). "On the other hand, expression levels of ADAM32 remained unchanged in HUH-6 and lung cancer cell lines, although an increase in CA9 expression was observed." (PMID 40507253, 2025). "CA9-targeting therapy is a promising approach to improve the therapeutic effect of gefitinib-resistant lung cancer by inducing ferroptosis." (PMID 36760347, 2023). "The results suggest that CA9 mRNA levels were commonly upregulated in gefitinib-resistant lung cancer tissues compared with sensitive tissues." (PMID 36760347, 2023). "Taken together, CA9-targeting therapy is a promising approach to improve the therapeutic effect of gefitinib-resistant lung cancer by inducing ferroptosis." (PMID 36760347, 2023). "Here, we show that CA9 is upregulated in gefitinib-resistant lung cancer and confers resistance to ferroptosis-inducing drugs." (PMID 36760347, 2023). "Then, we measured CA9 expression in lung cancer tissues biopsied from patients who benefitted from gefitinib and patients who acquired gefitinib resistance." (PMID 36760347, 2023). "Altogether, this study found that CA9 is upregulated in gefitinib-resistant lung cancer and confers resistance to ferroptosis-inducing drugs." (PMID 36760347, 2023). "At last, we only demonstrated that CA9-targeting therapy improved gefitinib-resistant lung cancer treatment." (PMID 36760347, 2023). "In the present study, we suggest that CA9 confers resistance to ferroptosis in gefitinib-resistant lung cancer cells by regulating iron metabolism." (PMID 36760347, 2023). "We have further confirmed this in another ongoing CA9-ko study involving lung cancer cells (unpublished data)." (PMID 28055960, 2017). "Even if further chemical optimization of TBZT is required to improve efficacy and specificity, these results suggest a possible application of TBZT for further development against lung cancer through its CA9 inhibitory activity." (PMID 22748168, 2012). "We performed additional experiments of CA9 immunostaining of 48 biopsy samples from the 338 lung cancer patients, because we could obtain the 48 biopsy specimens in our hospital and confirm to be histologically carcinoma." (PMID 39471162, 2024). "Here, we identified carbonic anhydrase IX (CA9) was upregulated in gefitinib-resistant lung cancer." (PMID 36760347, 2023). "Targeting CA9 has been demonstrated to induce ferroptosis in gefitinib-resistant lung cancer." (PMID 36760347, 2023). "In addition, elevated CA9 expression is closely related to poor prognosis in EGFR-mutant lung cancer." (PMID 36760347, 2023). "Inhibiting CA9 is a promising approach to improve lung cancer treatment by targeting ferroptosis." (PMID 36760347, 2023). "Furthermore, the carbonic anhydrase 9 (CA9), which is overexpressed in various cancer types such as breast and lung cancer, is also responsible for the low pH conditions in the TME." (PMID 36559202, 2022). "Carbonic anhydrase 9 (CA9) plays a vital role in lung cancer progression." (PMID 32365566, 2020). "Thus, further studies on whether CA9-targeting therapy improves osimertinib-resistant lung cancer treatment would be beneficial." (PMID 36760347, 2023). "For example, cetuximab was more cytotoxic against hypoxic than well-oxygenated A431 lung cancer cells grown in vitro and it reduced the overexpression of hypoxia markers like HIF-1α, CA9 and VEGF." (PMID 26032726, 2015).
lung carcinoma (continued). "For these reasons the A549 lung carcinoma cell line, which shows marked hypoxic induction of both VEGF and CA9, was chosen for these studies." (PMID 11953885, 2002). "In a variety of solid tumors, including CRC,19, 20 bladder cancer, non‐small cell lung cancer, triple‐negative breast cancer, and pancreatic cancer, CA9 has been widely confirmed as an oncogenic factor and diagnostic molecular marker." (PMID 36537608, 2023). "Compared to the nontumor tissues, we demonstrated significantly higher CA9 mRNA expression using the TCGA database (P < 0.001) and higher CA9 protein expression using the CPTAC database (P < 0.001) in lung cancer tissues." (PMID 36760347, 2023).
colorectal cancer (57 papers, 2003 to 2026). A primary or metastatic malignant neoplasm that affects the colon or rectum. "In previous studies on colorectal cancer, high expression of CA9 has been associated with poor outcomes in cancer patients." (PMID 41441010, 2025). "Stromal expression of hypoxia inducible factor 2α (HIF-2α) and carbonic anhydrase 9 (CA9) are associated with a poorer prognosis in colorectal cancer (CRC)." (PMID 18728663, 2008). "The CA9 gene was among four “hub” ferroptosis-related genes identified using machine learning and bioinformatics approaches to establish key genes and molecular interactions associated with ferroptosis in colorectal cancer." (PMID 38099193, 2023). "Interestingly, expression of CA9 was positively correlated with expression of transferrin receptor 2 (TFR2) in colorectal cancer, suggesting an association between CA9 and iron transport, which is a key process associated with ferroptosis." (PMID 38099193, 2023). "Furthermore, several studies focusing on increased intestinal CA9 expression suggested its association with the development of colorectal cancers, implicating the long‐term effects of consistent elevated CA9 expression." (PMID 31559135, 2019). "Second, although we demonstrated the functional significance of the dysadherin/CA9 axis in vitro and in vivo, therapeutic validation in colorectal cancer models remains limited." (PMID 41535258, 2026). "CA9 is a predictive indicator of survival in patients with leukaemia, colorectal cancer and urothelial cell carcinoma." (PMID 36415514, 2022). "Overexpression of HIF-1α and CA9 have also been shown to be powerful prognostic factors in colorectal cancers." (PMID 25789026, 2015). "Here, we demonstrated that CA9 gene polymorphisms, rs2071676, influenced colorectal cancer differentiation but did not affect the predisposition to CRC." (PMID 35812185, 2022). "Furthermore, enrichment of Wnt4 protein and carbonic anhydrase 9 (CA9) in TEVs in response to hypoxia were demonstrated to be responsible for increased angiogenesis in colorectal cancer." (PMID 34532325, 2021). "AGPAT4, ENTPD1, HADHB, CA12, CA9 was reported in colorectal cancer." (PMID 33815132, 2021). "Hypoxia increased cell viability and CA9 expression in colorectal cancer HCT-15 cells." (PMID 26447758, 2015). "The role of CA9 in colorectal cancer (CRC) remains to be clarified." (PMID 26447758, 2015). "In colorectal cancer cells, KDM4B expression is induced by HIF-1α, and KDM4B upregulates the expression of hypoxia-inducing genes such as carbonic anhydrase 9 (CA9) by decreasing H3K9me3 markers in the promoter." (PMID 35186950, 2021). "In this study the expression of CA9 was not prognostic in terms of overall survival, in contrast to a report that expression of CA9 is a poor prognostic factor in colorectal cancer." (PMID 19844231, 2009).
glioblastoma (57 papers, 2006 to 2025). The most malignant astrocytic tumor (WHO grade IV). "Downstream of HIF-1α are hypoxia responsive genes, including glucose transporter 1 (GLUT-1) and CA-IX (Carbonic Anhydrase 9) which are expressed in cells undergoing anaerobic metabolism and demonstrated to be overexpressed in glioblastoma cells." (PMID 37752585, 2023). "In the 11 control glioblastomas, the expression of CA9 was universally observed around many necrotic regions in eight (staining: ++), occasionally observed in two, and was nearly negative in one." (PMID 27244880, 2016). "HIF-1α or CA9 expression was decreased in five of the six tumors, whereas the decreased expression of these markers was noted in only one of the 11 control glioblastomas." (PMID 27244880, 2016). "An increase in hypoxia and the hypoxia-regulated genes CA9 and c-Met was identified in bevacizumab-resistant glioblastomas after treatment." (PMID 25700172, 2015). "Knock-down or inhibition of CA9, a key pH regulatory enzyme, enhanced bevacizumab therapy of colon and glioblastoma xenografts." (PMID 25700172, 2015). "Said and colleagues have shown that the specific chemical CA9 inhibitors, acetazolamide and SU.D2, are leading to an inhibition of CA9 in protein and mRNA levels during tumorgenesis of glioblastoma." (PMID 26447758, 2015). "CA9 was silenced in the human glioblastoma cell line, U373, which has a high basal level of CA9 expression." (PMID 22087255, 2011). "Molecular markers of hypoxia, such as HIF-1 and its downstream targets vascular endothelial growth factor (VEGF) and carbonic anhydrase 9 (CA IX), are consistently detected in glioblastoma using immunohistochemistry staining, while dynamic contrast enhanced MRI reveals tumor vascularity." (PMID 32631383, 2020). "The second gene chosen as experimental target was CA9, a gene already considered a promising target in breast, lung, colon, and bladder carcinomas, and in medulloblastomas and glioblastomas." (PMID 33153038, 2020). "In this study we performed 3D DESI-MS imaging using a heterotopic xenograft glioblastoma model to investigate lipid heterogeneity and immunofluorescence to find correlations between the MS lipid heterogeneity data and the downstream marker of hypoxic signalling, carbonic anhydrase-9 (CA-9)." (PMID 33020565, 2020). "Intraperitoneal injections of DT significantly inhibited the growth of established glioblastoma xenografts, and suppressed expression of HIF-1α and carbonic anhydrase (CA9), a surrogate marker of hypoxia." (PMID 28410215, 2017). "When comparing human patient-derived glioblastoma samples with normal brain, miR-210 expression is highly overexpressed in the tumors, and expression is highly correlated with both hypoxia markers VEGF and carbonic anhydrase 9 (CA9)." (PMID 32258065, 2020). "On the contrary, GSC_TMZ did not up-regulate CA9, MCT1, MCT4 mRNA expression, indicating that these proteins mediating intracellular pH and lactate transport may require a hypoxic microenvironment in glioblastomas." (PMID 35008590, 2021).